TULP1 (TUB like protein 1)
Diseases named in the same sentence as TULP1 in open-access papers (continued):
Sharing a sentence is not in itself a finding about the gene and the disease.
breast carcinoma (2 papers, 2025). "In the current study, we showed that anti-TULP1 autoantibodies were more prevalent among women with breast cancer and vision loss than in other patients." (PMID 40141211, 2025). "Anti-TULP1 AAbs were more prevalent in the subset of women with breast cancer and vision loss." (PMID 40141211, 2025). "This implies that the presence of anti-TULP1 AAbs are more distributed than was anticipated; however, their significantly high presence in breast cancer patients remains difficult to explain." (PMID 40141211, 2025). "The main question here is about the relationship of retinal TULP1 and breast cancer, or cancer in general." (PMID 40141211, 2025). "As of now, there is limited literature on the association of TULP proteins with cancer, although TULP1 is a possible ligand for the TAM family of kinases, and is overexpressed in cancers, including breast cancer." (PMID 40141211, 2025). "We discovered that a considerable number of women with breast cancer and vision disturbance had serum anti-TULP1 AAbs, often coexisting with other anti-retinal AAbs, including a case of anti-recoverin and anti-Rab6A being present in the same patient." (PMID 40141211, 2025). "In this cohort of TULP1 seropositive patients in women with breast cancer (n = 36/90), anti-recoverin (n = 12/90) and anti-Rab6 (n = 13/90) AAbs were found to be present along, with anti-TULP1, in the same patient." (PMID 40141211, 2025). "Because not much is known about the prevalence of anti-TULP1 AAbs in AIR and CAR as well in general healthy population, we focused this research on females with breast cancer and anti-TULP1 AAbs." (PMID 40141211, 2025). "The most interesting finding is that a significant number of women with diagnosed breast cancer were seropositive for anti-TULP1 AAbs." (PMID 40141211, 2025). "This study shows, for the first time, that a high prevalence of anti-TULP1 AAbs can be found in patients with vision disturbance and breast cancer compared to other patients." (PMID 40141211, 2025). "A total of 90 patients had a history of breast cancer, and anti-TULP1 AAbs were tested positive in 40% of this cohort." (PMID 40141211, 2025). "Third, there is a clear association between the presence of anti-TULP1 AAbs and breast CAR; however, the role of TULP1 in breast carcinoma or other cancer tissues is still unknown." (PMID 40141211, 2025). "Therefore, we focused on the occurrence of AAbs in 2453 patients whose sera were evaluated for anti-retinal Aabs; consequently, the sample of patients with breast cancer, vision disturbance, and anti-TULP1 is relatively small." (PMID 40141211, 2025). "Although we show a correlation of anti-TULP1 AAbs with breast cancer, we found no TULP1 protein expression in breast cells, making this association unclear." (PMID 40141211, 2025). "Our screening study of 37 malignant breast cancer tissue specimens for the presence of TULP1 was negative for the expression of this protein." (PMID 40141211, 2025). "We randomly selected anti-TULP1 AAb containing sera from breast cancer patients (n = 14) and no cancer patients (n = 13) for epitope searching by ELISA." (PMID 40141211, 2025).
chronic hepatitis C (2 papers, 2015 to 2024). "One study in 2342 chronic hepatitis C patients found that SNPs in two functionally related gene, MERTK and TULP1(tub like protein 1), encoding factors involved in the macrophage mediated phagocytosis of apoptotic cells were associated with liver fibrosis progression." (PMID 39201329, 2024). "European GWAS have identified SNPs in MERTK, GLT8D2, TULP1, and RNF7 as the genetic factors responsible for liver fibrosis progression in chronic hepatitis C during the natural course." (PMID 26352693, 2015).
ciliopathies (2 papers, 2020 to 2023). "The past studies indicate that mouse models of ciliopathies caused by Tulp1 and IFT88 mutations manifest rhodopsin mislocalization and accumulation of rhodopsin-laden vesicles, as was observed in this study." (PMID 32376599, 2020).
hyperopia (2 papers, 2019 to 2025). A refractive error in which rays of light entering the eye parallel to the optic axis are brought to a focus behind the retina, as a result of the eyeball being too short from front to back. "High hyperopia had the greatest representation from the BEST1 (n = 4, +6.69 ± 0.97D), RS1 (n = 4, +7.00 ± 2.00D), MFRP (n = 2, +12.31 ± 4.33D) and TULP1 (n = 2, +6.13 ± 1.24D) genotypes." (PMID 41465105, 2025). "Hyperopia is common in some IRDs including AD BEST1-retinopathy, RS1 and some LCA genotypes (in the current cohort: AIPL1, ALMS1, CEP290, CRB1, CRX, TULP1)." (PMID 41465105, 2025).
colorectal cancer (1 paper, 2025). A primary or metastatic malignant neoplasm that affects the colon or rectum. "One published study showed that expression levels of TULP3, a protein related to TULP1, were increased in colorectal cancer when compared to adjacent non-tumoral tissue." (PMID 40141211, 2025).
endometrial cancer (1 paper, 2025). Primary or metastatic malignant neoplasm involving the endometrium (mucous membrane that lines the endometrial cavity). "They found that this patient also had anti-recoverin in addition to anti-TULP1 AAbs and that both were present prior to the diagnosis of endometrial cancer." (PMID 40141211, 2025).
macular degeneration (1 paper, 2024). Loss of vision in the central portion of the retina (macula), secondary to retinal degeneration. "In our current research, we explore the clinical and molecular characteristics of a patient with biallelic TULP1 variants presented with a unique pattern of macular degeneration and periarteriolar vascular pigmentation." (PMID 38450199, 2024). "Discussion: Our data support that individuals with biallelic TULP1 variants may present with a unique pattern of macular degeneration and periarteriolar vascular pigmentation." (PMID 38450199, 2024).
cancer (5 papers, 2018 to 2025). A tumor composed of atypical neoplastic, often pleomorphic cells that invade other tissues. "Studies concerning the effects of TUBBY and TULP-1 in cancer are rare." (PMID 29386018, 2018). "All serum AAbs recognized the same 2 major lineal epitopes in the TULP1 sequence independent of cancer diagnosis, and some minor epitopes specific to each group." (PMID 40141211, 2025). "In summary, sera with anti-TULP1 antibodies labeled the same photoreceptor structures as commercial antibodies specific for TULP1 independently of whether they were from cancer patients or patients who had not been diagnosed with cancer." (PMID 40141211, 2025). "The epitope determination for anti-TULP1 AAbs conducted in our studies shows that anti-TULP1 AAbs may be generated due to photoreceptor degeneration initiated by other processes, rather than initiated by an immune response to cancer antigens." (PMID 40141211, 2025).
retinopathy (5 papers, 2020 to 2025). "It is only through a complete understanding of the photoreceptor compartment-specific function of Tulp1 that therapeutic strategies can be developed to treat this severe retinopathy." (PMID 34360830, 2021). "For example, TULP1-linked IRDs were originally identified as photoreceptor-based retinopathies, yet recent studies suggest both photoreceptor and non-photoreceptor expression of Tulp1/TULP1." (PMID 32973439, 2020). "We found that anti-TULP1 AAbs prevail in breast CAR; however, it is not clear how they contribute to the pathogenicity of retinopathy." (PMID 40141211, 2025).
tumor (1 paper, 2016). "What is the role of non-γ-carboxylated TAM ligands (Tubby, TULP-1, Galectin-3) in the tumor microenvironment?" (PMID 27916840, 2016).
TULP1 also shares sentences with these, for which no sentence is quoted: Obesity (3 papers); autosomal recessive retinitis pigmentosa (2); liver fibrosis (2); small cell lung carcinoma (2); Stargardt disease (2); achromatopsia (1); Autoimmunity (1); Bardet-Biedl syndrome (1); basal cell carcinoma (1); diabetes (1); glioblastoma (1); infection (1); Pigmentary retinopathy (1); renal carcinoma (1); Retinal atrophy (1); Type 1 Diabetes (1); uveitis (1).